CAV1 (caveolin 1)
Diseases named in the same sentence as CAV1 in open-access papers (continued):
Sharing a sentence is not in itself a finding about the gene and the disease.
virus infection (18 papers, 2011 to 2025). "Researchers have started to have deeper insights into the important mechanistic associations of caveolae and CAV-1, with all the stages during virus infection, despite that our understanding of the responses of infection-triggered cellular caveolae system is far from complete." (PMID 32357558, 2020). "Intriguingly, the versatile roles of caveolae/caveolin-1 in virus infections have increasingly been appreciated." (PMID 32357558, 2020). "In this section, we first introduce the widely-studied HIV and HBV in detail, followed by the regulation of CAV-1 in other viral infection-related signaling." (PMID 32357558, 2020). "Together, CAV-1 not only participates in the viral life cycle but also relates to a number of diseases induced by virus infections, which make CAV-1 a potential conservative treatment site for clinical diseases." (PMID 32357558, 2020). "Among those host antiviral mechanisms and hijacking machinery, there is a very important, yet less explored one, the caveolin-1 and formed membrane invagination caveolae-mediated virus infection." (PMID 32357558, 2020). "This review recapitulates our current knowledge on how caveolae/caveolin-1 functions in every step of the viral infection cycle and various relevant signaling pathways, hoping to provide a new perspective for future viral cell biology research." (PMID 32357558, 2020). "The upregulation of Cav-1 during viral infection can alter cholesterol composition modulate NCCLR, serving as initial danger signal and consequently leading to cell arrest and repression of viral transcription contributing to latent infection." (PMID 33121153, 2020). "IPEC-J2 cells were transfected with either caveolin-1 WT or DN plasmid caveolin-1 Y14F as well as control vector before virus infection." (PMID 30909932, 2019). "Cells treated with caveolae-mediated-endocytosis inhibitors became resistant to PSV entry, and caveolin-1 knockout as well as caveolin DN mutant transfection also inhibited virus infection." (PMID 30909932, 2019). "Previous in vitro studies using zebrafish cells revealed that Cav-1 was critical for antiviral signaling because when Cav-1 was depleted, clusters of Cav-1 molecules were dispersed, resulting in an abrogated immune response to virus infection." (PMID 25646724, 2015). "The observation of increased Src kinase activity specifically in caveolin-1 enriched fractions in infected cells strongly suggests a role for caveosomal signaling upon viral infection." (PMID 24147000, 2013). "Using the mouse adenovirus keratitis model, we then analyzed the role of caveolin-1 in viral infection." (PMID 24147000, 2013). "We demonstrate that upon virus infection, cav-1 is downregulated, circumventing the host antiviral IFN response." (PMID 23874753, 2013). "siRNA knock down of caveolin-1 in corneal cells reduced chemokine induction upon viral infection, and caveolin-1-/- mouse corneas showed reduced cellular entry of HAdV-D37." (PMID 24147000, 2013). "It has been shown that virus infection is inhibited by caveola destruction using a cholesterol-removing reagent and an RNAi method for caveolin-1." (PMID 22191032, 2011). "Caveolin-1 is the most important structural protein of caveolae, a type of membrane invagination widely known for its role in endocytosis and subsequent cytoplasmic transportation during virus infection." (PMID 41305477, 2025). "Moreover, we transfected the WT or DN constructs of caveolin-1 into PK15 cells prior to PCV3 infection to investigate the impact of overexpression on virus infection." (PMID 33679671, 2021). "In addition to the possible participation of the viral infection endosomal route, Cav-1 is also involved in the TGF-β pathway negative regulation." (PMID 35008594, 2021). "Importantly, accumulating studies revealed the versatile and multithreaded functions of caveolae and CAV-1 during virus infection." (PMID 32357558, 2020).
virus infection (continued). "Among host proteins directly interacting with virus proteins, the strongest connection with the ACE2 network occurs by ALB (30 interactors form ACE2 network) and CAV1 (13 interactors) which had affected the co-expression network after virus infection in hiPSC-CMs." (PMID 33233425, 2020). "We summarized the role of CAV-1-related signaling pathways in different virus infections." (PMID 32357558, 2020). "Similarly, SDC4, PIK3CA, and CAV1 genes showed upregulated expression upon viral infection, and after miR-124-3p mimic transfection and infection, their expression levels were decreased in hNS1 cells." (PMID 31578247, 2019). "Flavonoids could modulate the death of infected myocytes via Casp3 and CAV1 in the early stage of viral infection." (PMID 27023590, 2016). "In cells that were MβCD treated prior to virus infection, caveolin-1 was reduced." (PMID 24147000, 2013). "Interestingly, CAV1 was identified as a possible alternative receptor for SARS-CoV and Canine respiratory coronavirus (CRCoV), which may be associated with the virus infection, replication, assembly, and budding." (PMID 33233425, 2020). "The observation of colocalization between cav-1b-containing membrane domains and CRFB1 molecules led to the investigation of whether Cav-1 plays a role in the antiviral response to virus infection, since IFN is a critical component of the innate immune response." (PMID 23874753, 2013). "RNA interference silenced caveolin-1 expression in BHK-21 cells, in turn, impacted viral infection process as evident by the expression of VP1, virus titers and virus copies number." (PMID 33761945, 2021). "Recent reports show that this route depends on the lipid rafts, cellular membrane regions enriched by Cav-1 and ACE-2 receptors, endocytosed during the virus infection endosomal route." (PMID 35008594, 2021). "TFV MCP can be immunoprecipitated by anti-caveolin-1 antibody, suggesting that TFV MCP interacts with caveolin-1 at the late stage of virus infection." (PMID 26887868, 2016). "Upon viral infection, fractions 4-6 maximally expressed LAMP1 indicating the presence of late endosomes, while fractions 9-11 were enriched with caveolin-1, indicating the presence of caveolae." (PMID 24147000, 2013). "Our results revealed that before viral infection, inhibition of AnxA2 by A2ti-1 inhibitor suppressed ARV-modulated upregulation of the phosphorylation of Src, p38 MAPK, and caveolin-1 at Y14, as well as the expression levels of dynamin 2, at the 15- and 30-min time points." (PMID 37097149, 2023). "Similarly, upon viral infection, CXCL1 protein expression was reduced in caveolin-1 -/- mice as compared to wild type mice (p=.0001)." (PMID 24147000, 2013).
cardiac hypertrophy (17 papers, 2009 to 2025). "CAV1 has been reported to be cardioprotective and its absence is associated with cardiac hypertrophy." (PMID 31782728, 2019). "For example, Cav-1 deficient mice have showed cardiac hypertrophy owing to hyperactivation of ERK 1/2 signaling under basal conditions." (PMID 24454806, 2014). "Specifically, they showed that selective re-expression of Cav-1 in endothelium completely reversed cardiac hypertrophy and associated fibrosis." (PMID 26605130, 2012). "Is loss of Cav-1 expression in ECs the causative factor for cardiac hypertrophy?" (PMID 26605130, 2012). "Conversely, cardiac-specific CAV1 overexpression exacerbates cardiac hypertrophy and fibrosis, and further deteriorates cardiac dysfunction in diabetic mice." (PMID 40303344, 2025). "In fact, both genotypes of Cav-1-knockout (Cav-1-KO) and endothelium-specific eNOS transgenic (eNOS-Tg) mice disclosed altered cardiovascular phenotypes, including cardiac hypertrophy in Cav-1-KO mice and hypotension in eNOS-Tg mice." (PMID 36359402, 2022). "Caveolin-1-knockout mice exhibit myocardial hypertrophy due to constitutive activation of the p42/44 MAPK pathway and hyperphosphorylation of ERK1/2." (PMID 32257548, 2020). "Collectively, the cardiac-specific overexpression of caveolin-1 or caveolin-3 is a novel strategy to attenuate cardiac hypertrophy and heart failure." (PMID 32257548, 2020). "Cav1−/− mice have been shown to develop cardiac hypertrophy with decreased systolic function, even though Cav1 is expressed in atrial cardiomyocytes and endothelial cells but not in ventricular cardiomyocytes in the mouse heart." (PMID 27612189, 2016). "The expression of CaV1.2e21+22 diminishes during postnatal cardiac maturation and re-emerges in pressure-overload induced cardiac hypertrophy." (PMID 27731386, 2016). "Caveolin-1 knockout mice develop progressive cardiac hypertrophy as demonstrated by transthoracic echocardiography (TTE) and magnetic resonance imaging (MRI)." (PMID 20436850, 2009). "Other studies indicate that cardiac hypertrophy results in decreased expression of cav-3 and that right heart left heart hypertrophy is enhanced in caveolin-1 KO and caveolin-1/3 double KO mice." (PMID 20436850, 2009). "In contrast, cardiac hypertrophy was found to be reversed by the reconstitution of caveolin-1." (PMID 32257548, 2020). "NKX2-5, CAV1 and ATP2A2 in the integrin signaling and cardiac hypertrophy signaling (enhanced) pathways were also involved in the toxicity pathways such as failure of heart, congenital heart disease, congestive heart failure, dilation of heart chamber and dilation of left ventricle." (PMID 31948008, 2020). "The p42/44 MAP kinase could be activated in the absence of Cav‐1, leading to cardiac hypertrophy." (PMID 32508059, 2020). "Cav1 Cav3 double knockout animals, which completely lack caveolins because CAV2 is degraded in the absence of CAV1, develop cardiac hypertrophy and contractile failure." (PMID 31782728, 2019).
idiopathic pulmonary fibrosis (17 papers, 2011 to 2023). Idiopathic pulmonary fibrosis (IPF) is a nonneoplastic pulmonary disease that is characterized by the formation of scar tissue within the lungs in the absence of any known cause. "Interestingly, the apoptotic resistant phenotype of fibroblasts in idiopathic pulmonary fibrosis (IPF) also results from the down-regulation of Cav-1 via a PTEN/Akt-dependent pathway." (PMID 25658089, 2015).
prostate tumors (17 papers, 2008 to 2022). "The importance of stromal fibroblasts for the progression and radiation response of prostate tumors was further highlighted after co-implantation of Cav1-silenced PC3 cells with Cav1-proficient or -deficient HS5 fibroblasts as model." (PMID 28112237, 2017). "These survival analyses showed that high Cav-1 immunoreactivity in prostate tumor stroma was associated with a significantly longer cancer specific survival." (PMID 27764093, 2016). "In prostate tumor epithelium an up-regulation of Cav-1 has been reported and associated with high GS, extra-prostatic extension and lymph node involvement and with a poor outcome in patients treated with radical prostatectomy." (PMID 27764093, 2016). "Immunohistochemistry of human prostate tumour specimens revealed that Cav-1 expression is associated with microvessel density and expression of the endothelial cell marker and angiogenesis signalling receptor, VEGF-R2." (PMID 26328273, 2015). "In line with that idea, we show here that prostate tumors grown on Cav1-deficient mice were characterized by an increased tissue hypoxia as well as enhanced cell proliferation compared with tumors grown on wild-type controls." (PMID 25985209, 2015). "We previously reported that the radiation response of human prostate tumours is critically regulated by CAV1 expression in stromal fibroblasts and that loss of stromal CAV1 expression in advanced tumour stages may contribute to tumour radiotherapy resistance." (PMID 30871022, 2019). "In patients, expression of CAV1 in prostate tumors correlates with elevated metastatic potential and poor survival." (PMID 31362353, 2019). "Conclusively, the radiation response of human prostate tumors is critically regulated by Cav1 expression in stromal fibroblasts." (PMID 28112237, 2017). "Further, a low stromal Cav-1 expression in prostate tumors is related to advanced tumor stage and metastatic disease and increased risk of PSA-relapse after radical prostatectomy." (PMID 27764093, 2016). "ACC1 expression was significantly and proportionally higher in Cav-1+ areas in primary prostate tumors than in Cav-1-areas; this is a novel finding since the only known association between Cav-1 and ACC1 has been documented in adipose tissue." (PMID 27331874, 2016). "Taken together our data highlight a role of stromal Cav1 for the radiation response of prostate tumors." (PMID 25985209, 2015). "In conclusion, the radiation response of MPR31-4 prostate tumors is critically regulated by Cav1 expression in the tumor vasculature." (PMID 25985209, 2015). "To examine the role of stromal Cav1 in prostate tumor radiosensitivity, we first compared the response of MPR31-4 tumor xenografts to a single high-dose irradiation in Cav1 wild-type and Cav1-deficient mice." (PMID 25985209, 2015). "Our data indicate that radiation response of MPR31-4 prostate tumors is critically regulated by Cav1 expression in the tumor vasculature." (PMID 25985209, 2015). "Caveolin-1 is overexpressed and secreted in prostate tumors and promotes aggressiveness and angiogenesis." (PMID 24123650, 2013). "Here, the authors show that Cav-1 promotes rewiring of cancer cell lipid metabolism towards a program of exogenous lipid scavenging and vesicle biogenesis that intersects with mitochondrial dynamics in prostate tumors." (PMID 32855410, 2020). "Cav-1 is overexpressed in PCa, promotes prostate tumour progression and metastasis." (PMID 26328273, 2015). "Orthotopic prostate tumour xenografts of Cav-1-secreting cells (RM-9) in Cav-1 gene-disrupted mice or their wild type counterparts revealed that the mean tumour weight and microvessel densities in Cav-1(+/+) mice were higher than Cav-1(−/−) mice." (PMID 26328273, 2015). "Since cav-1 is a growth signaling molecule, it may serve as a surrogate for cell proliferation, which is the major feature of prostate tumor progression." (PMID 23934233, 2013).
prostate tumors (continued). "Analysis of the respective ceramide species in PCa cells with increased CAV1 levels like those typically found in radio-resistant advanced prostate tumors further revealed an upregulation of unsaturated C24:1 ceramide that might scavenge the effects of EC-derived apoptosis-inducing C16 ceramide." (PMID 32273493, 2020). "The sorting of CAV1-positive vesicles from the plasma of transgenic mice with autochthonous prostate tumors (TRAMP) showed that for this tumor model, microvesicles (>2 to 3 μm) larger than the exosome-sized particles could be detected and quantified in tissues and in circulation." (PMID 31362353, 2019). "Others tumor metastasis genes — Caveolin-1 (CAV1), H-Cadherin (CDH13), EPHA7, and S100A2 are often downregulated in prostate tumor tissues when compared to adjacent normal tissues due to methylation." (PMID 22547956, 2011). "To better define the relationship between lipid metabolism and Cav-1 within the context of the Cav-1-sphingolipid signature, we first compared gene expression profiles reflective of lipid managing apparati and mRNA expression of CAV1 in 333 prostate tumors using The Cancer Genome Atlas (TCGA)." (PMID 32855410, 2020). "The analysis of different areas of the same resection specimen revealed that the maintenance of endothelial Cav1 expression in advanced prostate tumors is not restricted to certain tumor areas with a particular Gleason grade but a general observation." (PMID 25985209, 2015). "CAV1 mediates the internalization of CDH1 and is up-regulated in prostate tumors." (PMID 22328933, 2012). "Immunoreactivity for Cav-1 was present in non-malignant (data not shown) and prostate tumor stroma." (PMID 27764093, 2016). "This suggests that high Cav-1 expression in prostate tumor stroma could perhaps be used as a marker for disease not needing treatment." (PMID 27764093, 2016). "Accordingly, high Cav1 expression is a negative prognostic factor for overall and disease-free survival in patients with various tumor types, including breast, esophagus, pancreas, kidney, and prostate tumors, meningioma and oligodendroglioma." (PMID 26315660, 2015).
thyroid cancer (17 papers, 2002 to 2025). "The role of caveolin-1 in other tumors, such as breast, pancreas, and thyroid cancer and cervical and head and neck SCC, is still controversial." (PMID 33037799, 2021). "We focused our attention on: CAV1, a 22 kDa protein considered as an indicator of thyroid carcinoma progression and serpinB2 (PAI2), a Plasminogen Activator Inhibitor that can reportedly act as a suppressor of tumor growth and metastasis formation." (PMID 29487711, 2018). "In the same research, they also reported that Galectin-3 and Cav-1 were required for RhoA GTPase activation and knocking down of either Galectin-3 or Cav-1 significantly reduced the migration of differentiated thyroid cancer cells." (PMID 29254179, 2017). "We have shown that pCav1 and Gal3 act together to stabilize FAK within FAs and promote FA dynamics and cell migration and that coordinate expression of Cav1 and Gal3 distinguish differentiated thyroid cancer from benign." (PMID 25942420, 2015). "Studies regarding the secreted type of caveolin-1 in thyroid carcinoma will be necessary in the future." (PMID 11953823, 2002). "Conversely, the decrease of Cav-1 in thyroid cancers could lead to a disruption of the thyroxisome and to a loss of normal hormonal synthesis." (PMID 35008579, 2021). "The upregulation of CAV1 expression in the presence of DEX may suppress caveolin’s yet undefined effects on 3D aggregation of thyroid carcinoma cells." (PMID 32033410, 2020). "Importantly, the synergistic or coordinating interaction between galectin-3 and caveolin-1 has been reported to promote tumor cell migration and invasion in thyroid cancer." (PMID 31252633, 2019). "We detected that factors inducing angiogenesis, the composition of integrins, the density of the cell monolayer exposed to microgravity, the enhanced production of caveolin-1, and the nuclear factor kappa B p65 could play a role during spheroid formation in thyroid cancer cells." (PMID 28273809, 2017). "No significant change was observed for CAV1 in a human thyroid cancer cell line after several minutes during sounding rocket flight, while and increase in levels was found during the hypergravity phase of the flight." (PMID 40577073, 2025). "CAV1 is not expressed in normal thyroid tissue but is highly expressed in thyroid cancer, especially in microcarcinoma." (PMID 37907864, 2023). "Further studies should be carried out regarding the mechanism of function and/or the lack of function of caveolin-1 in thyroid carcinoma." (PMID 11953823, 2002). "In a previous study of thyroid cancer, the reported proportion of caveolin-1-negative stroma was 78.9%, suggesting that the reverse Warburg effect may describe the situation in PTC." (PMID 28257096, 2017).